CDK4 (cyclin dependent kinase 4)
Diseases named in the same sentence as CDK4 in open-access papers (continued):
Sharing a sentence is not in itself a finding about the gene and the disease.
gastric cancer (continued). "In this paper, we reported that GL-1196, as a small molecular compound, effectively suppressed the proliferation of human gastric cancer cells through downregulation of PAK4/c-Src/EGFR/cyclinD1 pathway and CDK4/6 expression." (PMID 27077843, 2016). "Decreased miR-29a-3p expression promoted gastric cancer cell proliferation via reducing the expression of cell-cycle regulators including: CDK2, CDK4, and CDK6." (PMID 25889078, 2015). "Downregulation of cell cycle proteins, including cyclin D1, CDK4 and CDK6, was also observed in metformin-treated gastric cancer cells." (PMID 24351837, 2013). "Supporting findings from aggressive gastric cancer clinical samples with elevated SHCBP1, knockdown of SHCBP1 in gastric cancer cells suppresses the expression of CDK1, CDK4, and cyclin D1, consistent with a block at the G1/S phase transition and reduced cell proliferation." (PMID 41009347, 2025). "In addition, Piezo1 knockdown induced G1 phase block in gastric cancer cells and downregulated phosphorylated Rb, Cyclin D1, CDK4, and CDK6, suggesting that Piezo1 is required for gastric cancer cell proliferation." (PMID 38690080, 2024). "In the molecular level, DIM can arrest G1-phase cell cycle by reducing CDK4, and Cyclin D1 and elevating p21, a CDK (cyclin-dependent kinase) inhibitor.This finding is in line with previously reported mechanisms of DIM in gastric cancer and esophageal squamous carcinoma." (PMID 31396207, 2019). "Finally, correlation analysis revealed that FEZF1-AS1expression levels were positive correlation with SP1 and CDK2/CDK4/CDK6/CyclinD1 and inversely correlated with P21 expression levels in Gastric Cancer tissues." (PMID 28209170, 2017). "Using two TGF-β-sensitive gastric carcinoma cell lines (SNU-16 and -620), we addressed the contributory roles of several cdk inhibitors, and of cdk4 and Cdc25A, in TGF-β-induced cell cycle arrest by comparing their temporal expression pattern in response to TGF-β." (PMID 10376964, 1999). "For instance, ectopic transfections of miR-34c were reported to inhibit the growth of gastric cancer cells through suppression of the expression of cyclin-dependent kinase 4 (CDK4) and cyclin E2 (CCNE2) even if no direct interaction was demonstrated between the miRNA and these mRNAs." (PMID 32230926, 2020). "Indeed, the expression of CDK4, CDK6 and cyclin D1, which are expressed predominantly in the G1 phase and promotes the transition to S phase of the cell cycle, closely correlated with the expression of YES1 and YAP1 in gastric cancer cells and tumor xenografts." (PMID 35017464, 2022). "On the contrary, the cell cycle–related molecules are abnormal in over 50% of the patients with gastric cancer (GC), but the efficiency of inhibiting CDK4/6 does not work well as it is expected." (PMID 34513922, 2021). "We have confirmed that the expression of PGRN and CDK4 was both increased and positively correlated in gastric cancer, but it was not clear whether the upregulated PGRN regulated the cell cycle via CDK4." (PMID 35880418, 2022).
neuroblastoma (67 papers, 2013 to 2025). Neuroblastoma (NB) is the most common solid, extracranial childhood tumor. "Several of these targeted agents have shown efficacy in pediatric cancers, as in the use of ALK inhibitors such as crizotinib in ALK-mutated neuroblastoma (NB) and CDK4/6 inhibitors including Palbociclib in pediatric sarcomas." (PMID 38347552, 2024). "While Rb1 loss is very rare in neuroblastoma, several studies have shown that the cyclin D/CDK4/CDK6 pathway is hyperactive in neuroblastoma." (PMID 34893606, 2021). "In neuroblastoma cells, CDK4/6 inhibition caused cell-cycle arrest and cellular senescence that was correlated with dose-dependent decreases in phosphorylated RB and FOXM1, respectively." (PMID 33806615, 2021). "Recent in vitro and in vivo studies on the therapeutic utility of inhibitors targeting the cyclin D1-associated kinases CDK4/CDK6 revealed promising results in various cancer types including neuroblastoma." (PMID 29719597, 2018). "E2F family deregulation especially occurs in recurrent neuroblastomas and tumor-derived cell lines, presumably caused by upregulation of factors, such as CDK4, that inhibit the RB1 tumor suppressor." (PMID 28036269, 2017). "In addition, research for malignant glioma, neuroblastoma and malignant peripheral nerve sheath tumors demonstrated that CDK4 copy number was amplified and was associated with tumor prognosis." (PMID 31358010, 2019). "CDK4 is highly expressed and associated with poor prognosis and decreased survival in advanced neuroblastoma (NB)." (PMID 39087955, 2024). "In addition, the NEPENTHE study at the Children’s Hospital of Philadelphia is studying the combination of ribociclib and trametinib for patients with relapsed neuroblastoma whose tumors harbor activating mutations in the RAS-MAPK or CDK4/6 pathway (NCT02780128)." (PMID 30326621, 2018). "A phase I trial of the CDK4/6 inhibitor ribociclib in paediatric patients with RTs, neuroblastoma, and other solid tumours showed acceptable safety and prolonged stable disease in a subset of patients." (PMID 40422882, 2025). "To understand this further, we analyzed our targeted CRISPR screens in the 10 neuroblastoma cell lines, noticing the cell cycle regulator CDK4 knockout was the #2 ranked sensitization hit." (PMID 40021625, 2025). "Cell division is controlled by a complex of cyclin and cyclin-dependent kinases (CDKs), and in neuroblastoma, CDK4/6 inhibitors are of particular interest." (PMID 40104501, 2025). "Recently, we have shown that cell cycle lengthening with the CDK4/6 inhibitor palbociclib promotes differentiation in neuroblastoma cell lines." (PMID 41358253, 2024). "We have previously shown that the CDK4/6 inhibitor palbociclib induces both decreased proliferation and enhanced neuronal differentiation of neuroblastoma cellsin vitro." (PMID 41146951, 2024). "Altogether, these results support the clinical significance of the interaction network formed by CDKN3, CDC6 and CDK4 in neuroblastoma." (PMID 38356706, 2024). "We therefore conclude this is a class effect; all CDK4/6 inhibitors have a combinatory effect with retinoic acid in inducing differentiation of neuroblastoma cells." (PMID 41146951, 2024). "For example, the co-amplification and resulting overexpression of MDM2/CDK4/FRS2 in neuroblastoma patient M787AAA is clinically relevant, and the fusions originating from this amplification are more likely to be passenger events." (PMID 37400763, 2023). "Regarding childhood cancers, the use of CDK4/6 inhibitors has been applied only once on a small cohort of young patients affected by different types of tumors such as neuroblastoma, MRT, and rhabdomyosarcoma." (PMID 36982482, 2023).
neuroblastoma (continued). "Here, we show that the CDK4/6 inhibitor palbociclib not only inhibits proliferation but induces extensive neuronal differentiation of adrenergic neuroblastoma cells." (PMID 37734383, 2023). "In a mouse xenograft model of neuroblastoma with ALK F1174L and F1245C mutations, the CDK4/6 inhibitor ribociclib blocks the binding of CDK4/6 to CyclinD1, thereby inhibiting the operation of the cell cycle." (PMID 35211406, 2022). "Pharmacological inhibition of CDK4/6 with ribociclib or abemaciclib decreased proliferation in a broad set of neuroblastoma cell lines, including CDK4/MDM2-amplified, whereas MDM2 inhibition by Nutlin-3a was only effective in p53wild-type cells." (PMID 35859155, 2022). "With respect to neuroblastoma, LEE011, a highly specific CDK4/6 inhibitor caused cell-cycle arrest and cellular senescence in a large subset of neuroblastoma cell line and Xn models." (PMID 35884854, 2022). "MCM6 acts as a tumor promoter by activating CDK4-Cyclin D1 signaling, and subsequently regulates cell cycle progression in G1/S phase in neuroblastoma." (PMID 34233647, 2021). "In summary, we have defined a chromatin-dependent mechanism of action of KDM6B inhibition that modulates the CDK4/6-pRB-E2F pathway in neuroblastoma." (PMID 34893606, 2021). "Overexpression of CDK4/6 or Rb1 knockout confers neuroblastoma cell resistance to both palbociclib and the KDM6 inhibitor GSK-J4." (PMID 34893606, 2021). "Overexpression of CDK4 or CDK6 conferred expected resistance in neuroblastoma cells to palbociclib, as shown by colony formation and EC50 shift." (PMID 34893606, 2021). "CDK4/6 expression is upregulated in 30% of neuroblastomas resulting in E2F overexpression and S and G2/M phase progression, and is another attractive therapeutic target." (PMID 34722256, 2021). "It has been reported that the CDK4/6 inhibitor, palbociclib, consistently induces G1 cell cycle arrest in neuroblastoma cell lines and reduces levels of phosphorylated Rb." (PMID 34069817, 2021). "Here the authors show that KDM6B regulates CDK4/6-pRB-E2F pathway through H3K27me3-dependent enhancer-promoter interactions in neuroblastoma." (PMID 34893606, 2021). "The combination of ceritinib and the CDK4/6 inhibitor, ribociclib, has been studied extensively in preclinical models of ALK mutated neuroblastoma." (PMID 30326621, 2018). "BLF1 caused a down-regulation of the eIF4A-sensitive oncogenic protein CDK4 which has previously been shown to be important for maintaining an undifferentiated phenotype in neuroblastoma cell lines." (PMID 29954071, 2018). "Aside from CDK4 and 6, other CDKs have been examined as potential targets for neuroblastoma treatment given their importance in cell proliferation through regulation of the cell cycle." (PMID 26771642, 2016). "Recently, it has been shown that inhibition of CDK4/6 by LEE011 reduces the growth of neuroblastoma tumors with MYCN amplification in murine xenograft models." (PMID 26225123, 2015). "Palbociclib also induces hypophosphorylation of Rb at Ser780, indicative of CDK4/6 inhibition, in those neuroblastoma cell lines that show a reduction in cellular proliferation after treatment." (PMID 26225123, 2015). "Only the neuroblastoma cell line CHP-212 showed a relevant decrease in cell viability when incubated with the CDK4,6i palbociclib." (PMID 25277205, 2014). "Only the neuroblastoma cell line CHP-212 showed a relevant reduction in cell viability in response to treatment with the CDK4,6i palbociclib." (PMID 25277205, 2014). "Inhibition of the G1 regulating genes CDK4 or Cyclin D1 in neuroblastoma cell lines lead to the restoration of the G1 checkpoint and subsequent neuronal differentiation." (PMID 23383150, 2013). "Here, we find that three independent CDK4/6 inhibitors all induce neuroblastoma differentiation, confirming the hypothesis that G1 lengthening is a key mechanistic trigger for this process." (PMID 41146951, 2024).
neuroblastoma (continued). "Recently, we have shown that combinatorial treatment with the CDK4/6 inhibitor palbociclib and differentiation-inducing agent retinoic acid inhibits proliferation and drives neuronal differentiation of adrenergic-type neuroblastoma cell lines." (PMID 41358253, 2024). "We find that CDK4/6 inhibitors display a class effect in inducing neuronal differentiation together with retinoic acid, both in two-dimensional and three-dimensionalin vitro neuroblastoma cell cultures." (PMID 41146951, 2024). "In summary, we find that CDK4/6 inhibitors display a class effect in reducing proliferation and inducing neuronal differentiation together with retinoic acid, both in two-dimensional and three-dimensionalin vitro neuroblastoma cell cultures." (PMID 41146951, 2024). "In this study, we investigated the response of neuroblastoma cells to the CDK4/6 inhibitor PB." (PMID 37734383, 2023). "Based on that, we speculated that in the context of amplified MYCN, a positive RB1 expression might positively sensitize neuroblastoma cells to CDK4/6 inhibitors." (PMID 36982482, 2023). "A phase I study of the CDK4/6 inhibitor in pediatric patients with malignant rhabdoid tumors, neuroblastoma, and other solid tumors, displays an acceptable safety profile, dose-dependent pharmacokinetic characteristics, and preliminary signs of tumor stabilization." (PMID 37591827, 2023). "Interestingly, CDK4, rather than CDK6, is essential for the proliferation of adult oligodendrocyte progenitor cells, and knockdown of CDK4 in neuroblastoma cells reduces their proliferation." (PMID 34625907, 2022). "Here we present detailed biological data of an aggressive neuroblastoma subgroup hallmarked by 12q amplification and atypical clinical presentation for which our in vitro studies indicate that CDK4 and/or MDM2 inhibition also could be beneficial." (PMID 35859155, 2022). "With this approach, we found that genes downregulated by KDM6B knockdown in neuroblastoma cells overlapped significantly with the transcriptomes downregulated by palbociclib, a specific CDK4/6 inhibitor that acts upstream of the E2F pathway in cell cycle regulation." (PMID 34893606, 2021). "Thus, our studies reveal that KDM6B regulates the oncogenic CDK4/6-pRB-E2F pathway in MYCN-amplified neuroblastoma, revealing a mechanism of regulation of the E2F transcriptome by an epigenetic modulator." (PMID 34893606, 2021). "A majority of neuroblastoma models with MNA are sensitive to CDK4/6 inhibition." (PMID 34893606, 2021). "In addition, binimetinib acts synergistically with the CDK4/6 inhibitor, ribociclib, to suppress tumor growth in murine neuroblastoma xenografts." (PMID 30326621, 2018). "Similarly, the CDK4/6 inhibitor LEE011 can also induce senescence in neuroblastoma cells through targeting the induction of FOXM1 by CDK4/6." (PMID 29180117, 2018). "Our data suggest that the CDK4/CDK6 inhibitor palbociclib may offer therapeutic benefit for the treatment of neuroblastoma." (PMID 26225123, 2015). "Selective inhibition of CDK4/6 using palbociclib may provide a new therapeutic option for treating neuroblastoma." (PMID 26225123, 2015). "Additionally, Moqidem suggested that cell death induced by A. vulgaris on SH-SY5Y human neuroblastoma cell line was through apoptosis induction accompanied by significant downregulation of the cell cycle genes (CDK4, CDK6 and E2F3), and upregulation of the tumor suppressor gene PTEN." (PMID 36015443, 2022). "In order to examine whether this comparative overexpression of transcripts was correlated with protein levels, we assessed by western blotting the expression of CDK4, cyclin D1 and Rb in Ewing sarcoma cells, mesenchymal stem cells, leukemia cell lines and neuroblastoma cells." (PMID 26337082, 2015). "Clinical trials with MEK inhibitors for neuroblastoma are ongoing (NCT06104488 and NCT02124772) in single treatment or in combination with CDK4/6 inhibitor ribociclib and BRAF inhibitor dabrafenib." (PMID 40854877, 2025).
neuroblastoma (continued). "• Binimetinib is effective in preclinical models of neuroblastoma tumors with low NF1 expression.• Binimetinib and CDK4/6 inhibitors are synergistic in preclinical models of neuroblastoma." (PMID 40115016, 2025). "JMJD3 inhibition has also been shown to cause the accumulation of H3K27me3, disturbing the interaction of transcription factors and resulting in the downregulation of the CDK4/6-pRB-E2F pathway and of MYCN in neuroblastoma." (PMID 40253363, 2025). "Known neuroblastoma-related genes such as MYCN, TERT, ODC1, CDK4, and MDM2 were recurrently affected by different classes of complex rearrangements including ecDNA, chromothripsis, and CnCs." (PMID 37868040, 2023). "The neuroblastoma patient has a focal amplification in chromosome 12q13-15 involving the oncogenes MDM2 and CDK4 (4–6 copy number log2 fold change, CN l2fc)." (PMID 37400763, 2023). "Cyclin-dependent kinase 4 (CDK4) is one of the putative transcriptional targets of MYC and is highly expressed in neuroblastomas with MYCN amplification." (PMID 34069817, 2021). "Several cell cycle regulators, especially those within the cyclin D1/CDK4/CDK6/RB pathway, are hyperactive in neuroblastoma." (PMID 29719597, 2018). "The specific CDK4/6 inhibitor, ribociclib/LEE011, reduced proliferation in MYCN-amplified neuroblastoma in vitro and decreased growth of murine neuroblastoma xenografts." (PMID 26771642, 2016). "Several cell cycle regulators, such as PLK1, TRIM16, WEE1, CDK4/6, and CCND1, have been shown to be involved in the tumorigenesis of neuroblastoma." (PMID 26225123, 2015). "In neuroblastoma (NB), genomic amplifications of CCND1 and cdk4 were observed in primary tumors, albeit at low frequency." (PMID 26029996, 2015). "Western blot analysis showed that G9a knockdown also led to a marked down-regulation of CyclinD1, CDK4 and CDK6 in the three neuroblastoma cell lines." (PMID 25198515, 2014). "CDK4/6 is crucial for the G1- to S-phase transition and abnormalities in CDK4/6 and the NF1 (a negative regulator of RAS activity) gene may contribute to neuroblastoma and malignant peripheral nerve sheath tumors." (PMID 38001644, 2023). "Dual inhibition of CDK4/CDK6 by LEE011 is reported to cause cell cycle arrest and induces senescence in 12 out of 17 neuroblastoma cell lines, but not all the tested cell lines were sensitive to LEE01127." (PMID 27378523, 2016). "Previous studies have shown that ALK inhibition synergizes with chemotherapy or CDK4 inhibition in preclinical models of neuroblastoma, and a clinical trial (NCT02780128) for testing the combination of ceritinib and ribociclib in ALK-mutant neuroblastoma patients is ongoing." (PMID 28425916, 2017). "Furthermore, the chromosome 12q arm contains other – in neuroblastoma not infrequently amplified – genes, among them oncogenes and cell cycle-associated genes (MDM2, CDK4, OS9, and GLI1)." (PMID 25161957, 2014).